CCT8L1P (chaperonin containing TCP1 subunit 8 like 1, pseudogene)
Description:
Possible molecular chaperone; assists the folding of proteins upon ATP hydrolysis.
Synonyms: CCT8L1
Gene: Processed pseudogene on chromosome 7 (152,445,477 to 152,447,150, forward strand). Ensembl gene ENSG00000020219.
Subcellular location: Cytoplasm